INS (insulin)
Diseases named in the same sentence as INS in open-access papers (continued):
Sharing a sentence is not in itself a finding about the gene and the disease.
diabetes (continued). "In participants without diabetes, vigorous EEE increased insulin sensitivity as compared to non-vigorous EEE (OR 1.53 (95% CI 0.01 to 3.07) vs. 1.71 (−0.35 to + 3.81))." (PMID 32867079, 2020). "Furthermore, contrary to the adaptive pancreatic response to exercise in the person without diabetes, the physiological and metabolic shifts with exercise may increase circulating insulin concentrations that may contribute to exercise-related hyperinsulinemia and consequent hypoglycemia." (PMID 33193089, 2020). "Patients with a history of acute illness, chronic liver and kidney disease, diabetes, cancer, malnutrition and drug use, women who were pregnant or breastfeeding, and subjects who were taking anticonvulsants or glucocorticoids were excluded as these may affect insulin and glycosuria levels." (PMID 32095207, 2020). "Type 2 diabetes mellitus (T2DM) is the most prevalent (∼85%), and it occurs due to tissue resistance or lack of insulin." (PMID 33552541, 2020). "To examine this issue, we recruited 79 subjects with T2D and refractory diabetes (RT2D), and all subjects received standard therapy with Metformin or other hypoglycemic agents with or without insulin for at least one year." (PMID 32899513, 2020). "Based on the types of diabetes medications, there were three groups among DM patients (the combined cohort of DM-only and DM+HTN groups), including metformin (n = 63), non-metformin oral hypoglycemic agent (OHA) (n = 104) and regular insulin (RI)/neutral protamine hagedorn (NPH) groups (n = 29)." (PMID 33382703, 2020). "Age, BMI, waist circumference, and levels of insulin and CPR were positively correlated with HbA1c quartile among the participants without diabetes." (PMID 31222973, 2020). "In patients with diabetes, vigorous EEE did not improve insulin sensitivity (Odds Ratio (OR (Odds Ratio)) 0.86; 95% CI −1.06 to + 2.82), whereas non-vigorous EEE did improve insulin sensitivity significantly (OR 2.64 (95% CI 0.11 to 2.64)." (PMID 32867079, 2020). "Obese subjects with and without diabetes who lose weight essentially reduce their IMCL content and improve their insulin sensitivity." (PMID 32903666, 2020). "The study on this long-term diabetes model showed that taurine had reduced the blood glucose levels, improved OGTT measurements and reduced insulin resistance without affecting the β cell function or pancreatic islet mass." (PMID 32172503, 2020). "Experimentally induced diabetes in rats significantly (p ≤ 0.001) elevated blood glucose, ALT, and AST levels, while diminished insulin level (p ≤ 0.05), in STZ group as compared with the nondiabetic control group." (PMID 33488745, 2020). "Therefore, we sought to determine whether hyperbaric oxygen would ameliorate insulin sensitivity by promoting glucose transporter type 4 (GLUT4) expression in muscle and by stimulating UCP1 in brown adipose tissue (BAT) in a streptozocin (STZ)-induced type 2 diabetes mellitus (T2DM) mouse model." (PMID 32082261, 2020). "It is clear now that kidney is not a mere target of insulin action, but insulin, more precisely IR, is also able to trigger CKD even in absence of diabetes." (PMID 32850773, 2020). "Type 2 diabetes mellitus (T2DM) is a noncommunicable metabolic disorder, characterized by the presence of chronic hyperglycemia, due to inadequate production of insulin and defect in insulin sensitivity." (PMID 32438746, 2020). "Type 1 diabetes mellitus (T1DM) is an immune-mediated disorder that results from autoimmune destruction of pancreatic islet ß cells, which leads to little or no insulin production and uncontrolled high blood glucose levels." (PMID 32405365, 2020).
diabetes (continued). "In women, cases tended to be older, had higher BMI and longer duration of diabetes, higher SBP, HbA1c, HDL-C, LDL-C, and SCR, and were less likely to use insulin and statins than patients without DN." (PMID 33633688, 2020). "Another commonly used medication for diabetes, insulin, could also increase the proliferation of nonbutyrate-producing bacteria, while butyrate-producing bacteria in the gut, such as Roseburia intestinalis and Eubacterium hallii, could improve insulin sensitivity." (PMID 32634783, 2020). "In the obese without diabetes group, a statistically significant increase in VO2 max and decreased percent body fat and insulin levels were observed." (PMID 32606431, 2020). "However, the study did not demonstrate the success of inducing diabetes by measuring baseline and final blood sugar level and/or insulin since α-tocotrienol possesses an antioxidant activity that could provide protection against the destructive effect of streptozotocin (STZ) on pancreatic β-cells." (PMID 32085610, 2020). "To attain greater clinical benefit, we also assessed the survival effects between different diabetes medications, including metformin, non-metformin oral hypoglycemic agents (OHA) and regular insulin (RI)/neutral protamine hagedorn (NPH)." (PMID 33382703, 2020). "Islets lacking UCN3 show increased insulin secretion and the exogenous administration of UCN2 normalized glucose levels in two distinct murine models of diabetes and increased glucose uptake in the skeletal muscles of obese mice." (PMID 32244319, 2020). "A similar trial has recently revealed that the transplanted mesenchymal cells not only differentiated into insulin-secreting cells but also did not incur immune reaction in the subjects, and therefore reveals promising future for MSC in diabetes therapy." (PMID 31547868, 2019). "DM occurs when blood glucose homeostasis is impaired because either the pancreas is no longer producing insulin, which is called type 1 diabetes (T1DM), or the cells in the body have difficulty responding to insulin properly, which is called type 2 diabetes (T2DM)." (PMID 31208980, 2019). "Furthermore, at the beginning of the study, we did not obtain information about diabetes complications, such as microangiopathy or macrovascular disorders, disease duration, or endogenous insulin secretion; therefore, we could not analyze the effects of these parameters on hypoglycemia." (PMID 31486247, 2019). "Patients were stratified post hoc into the following categories: without diabetes (n = 1337), with diabetes treated with oral antidiabetic drugs (OAD; n = 387) and with diabetes treated using insulin (n = 276)." (PMID 31138207, 2019). "A new study demonstrated that insulin-specific CAR-Tregs were functional, suppressive and surviving in vivo even though they were not able to prevent spontaneous diabetes in NOD mice." (PMID 31561568, 2019). "Compared with prediabetes and nondiabetes, adults with diabetes had significantly higher mean BMI, WC, triglycerides, TG/HDL cholesterol ratio, insulin, mean systolic blood pressure, and total co-morbidities (p < 0.001)." (PMID 30995902, 2019). "As for insulin sensitivity, the difference was still significant in the NGT group, but the difference did not remain significant in the diabetes group." (PMID 31690291, 2019). "We failed to observe any difference in INS mRNA between groups but the insulin response following exercise (Post-6) in the PD group may shed light on an interesting relationship between the progression of diabetes and differing glucoregulatory responses between PD and CON following exercise." (PMID 29351335, 2018). "ZnT8A were demonstrated in 5 of 11 patients with negative results for classical diabetes antibodies [insulinoma antigen-2 antibody (IA-2A), glutamic acid decarboxylase (GAD) or insulin autoantibodies]." (PMID 28943512, 2018).
diabetes (continued). "These included BMI, a family history of diabetes, non-white ethnicity, advanced maternal age, an early diagnosis of GDM, the fasting and post-glucose load PG, the HbA1c level, the use of insulin, multiparity, hypertensive disorder, and preterm delivery." (PMID 29310607, 2018). "In middle-aged adults with both diabetic and non-diabetic histories, insulin-sensitizing TZD compounds improve insulin sensitivity and glucose tolerance, and increase the likelihood of regression from pre-diabetes to normal glucose regulation." (PMID 29747466, 2018). "However, insulin analogues may not be suitable for all patients with diabetes." (PMID 29755520, 2018). "These positive effects were observed even though the studies were conducted on healthy people, without metabolic syndrome, pre-diabetes or T2DM, and with normal insulin secretion." (PMID 30044398, 2018). "Level of diabetes knowledge: Overall respondents' mean score on DKT was 10.4 (2.8) considering total knowledge, for general knowledge 6.4 (1.9) and for insulin use knowledge 4.1 (1.8) (data not shown)." (PMID 30050608, 2018). "Second, we jointly analyzed three distinct diabetes-related glycemic traits measured at visit 4 in 5068 nondiabetic white participants measured at visit 4 in ARIC: fasting glucose, fasting insulin, and glucose level 2 hours after an oral glucose challenge." (PMID 29743933, 2018). "Another recent study revealed that post-challenge insulin concentration but not HbA1c, fasting glucose, insulin, or post-challenge blood glucose level can differentiate between CAD and cardiac syndrome X in subjects without known diabetes." (PMID 30110378, 2018). "A systematic review and meta-analysis showed that probiotics can improve the FBG level, insulin concentration, and the HOMA-IR score of patients ≥18 years of age with or without diabetes." (PMID 30388861, 2018). "Moreover, they suggest that insulin administration to maintain blood glucose within the conventional target range may be unnecessary in many critically ill patients with diabetes, irrespective of their premorbid glycemic control, illness severity, reason for ICU admission, and septic state." (PMID 30455957, 2018). "Although some studies have shown that improvement in standards of glycemic control and diabetes care has reduced the prevalence of LJM, the Diabetes Control and Complications Trial (DCCT) could not show a consistent association between intensive insulin therapy and the elements of cheiroarthropathy." (PMID 29853876, 2018). "However, according to our data those patients with BMI over 35 kg/m2 treated with different insulin regimes regardless of baseline HbA1c level and duration of diabetes could benefit from this specific combination with regard to not only weight and hypoglycemia reduction, but also HbA1c improvement." (PMID 29563974, 2018). "Type 2 diabetes mellitus (T2DM) is characterized by absent responsiveness of body tissues to insulin, namely, insulin resistance." (PMID 29435181, 2018). "Though regular intravenous insulin injection is used to manage T1DM, this management strategy neither cures nor prevents onset of diabetes-induced complications." (PMID 30285704, 2018). "Type 2 diabetes mellitus (T2DM) is a long-term metabolic disorder that is characterized by high blood sugar, insulin resistance, and a relative lack of insulin." (PMID 30521626, 2018). "There were neither significant differences of age, sex, duration of diabetes, nor hs-CRP or insulin treatment between GADA positive and negative group observed in elderly diabetes." (PMID 29887833, 2018). "Type 2 diabetes mellitus (T2DM) is a metabolic and complex disease that is characterized by hyperglycemia in the context of insulin resistance and relative lack of insulin." (PMID 28179884, 2017). "No other associations were observed between inflammation-related markers and insulin, GIP, or PP among people who did not report a history of diabetes." (PMID 28753646, 2017).
diabetes (continued). "For instance, adenovirus-mediated delivery of Pdx1 or Ngn3 was shown to induce insulin expression by the liver, whereas AAV-mediated overexpression of the same TFs did not result into insulin production or correction of diabetes in mice." (PMID 28193997, 2017). "Compared to diabetes patients with PAD, patients without PAD (71.4% versus 10.9%) were more likely to be treated with oral hypoglycaemics and insulin [OR = 2.23 (1.08–4.59), p = 0.03]." (PMID 29445546, 2017). "While the majority of insulin-specific CD4 T cells in NOD mice are anergic, this form of tolerance is not sufficient o halt diabetes." (PMID 29259578, 2017). "Majority of patients were on combination oral anti-diabetes medicines (42.3%) and did not use insulin for their diabetes management, followed by combination of oral hypoglycemic agents (OHA) and insulin (39.2%)." (PMID 28702453, 2017). "Running our analysis replacing country specific prices for insulin and oral medication with PAHO–SF’s prices (plus 15%) in our data, resulted in cutting direct cost in 50% and the per capita cost of diabetes care by 35% (data not shown)." (PMID 29163935, 2017). "Patients with diabetes are typically classified as having Type 1 (T1DM), Type 2 (T2DM) or gestational diabetes based on the lack of insulin production, insulin resistance or insulin resistance during pregnancy, respectively." (PMID 28253317, 2017). "In conclusion, diabetes promotes CKD progression of AKI via activation of the TGF-β1 and Shh signalling pathways, but insulin treatment was not enough for preventing the progression of renal fibrosis." (PMID 29196746, 2017). "Type 2 diabetes mellitus (T2DM) is a long-term metabolic disorder that is characterized by high blood sugar, insulin resistance, and relative lack of insulin." (PMID 28273212, 2017). "Type 1 diabetes mellitus (T1DM) is characterized by an absolute lack of insulin and thus is dependent on exogenous insulin treatment." (PMID 28480220, 2017). "Since reduced IDE in the cytosol is not able to degrade all the internalized insulin, increased intracellular IDE would be beneficial for the improvement of diabetes." (PMID 28070499, 2017). "Furthermore, also regardless of HNF4A mutation carrier status or diabetes status, the S7 cells displayed the same GSIS kinetics, the same ultrastructural features and the same levels of proteomics-based protein markers of a mature β-cell, including INS, PDX1, NKX6.1, MAFA, GLUT2, UCN3 and others." (PMID 28684784, 2017). "Type II diabetes mellitus (T2DM) is primarily characterized by metabolic disorders and abnormally high blood sugar (hyperglycemia) because of low insulin levels with or without abnormal resistance to insulin action; T2DM accounts for 90% of diabetes cases." (PMID 29348892, 2017). "When analysis was limited to diabetes only group, the comparison was made against life style modification group and we did not identify significant protective effect from OHA or insulin at baseline." (PMID 27195294, 2016). "We did not observe different OPN levels in relation to diabetes, when we compared diabetics, irrespective of treatment, with nondiabetics but OPN was higher in patients on insulin versus those without insulin." (PMID 27597799, 2016). "Therefore, we examined whether long-term administration of GEB has hypoglycemic activity, and its action mechanism was explored in partially-pancreatectomized rats that exhibit similar characteristics as Asian type 2 diabetes, non-obese insulin-insufficient diabetes." (PMID 26978400, 2016). "In Alzheimer’s, neurons can become both insulin- and IGF-1-resistant, even absent the clinical diagnosis of diabetes, with elevations in IRS-1 serving as a biomarker for brain insulin-resistance." (PMID 26823968, 2016). "The findings from this study will inform the next generation of diabetes education, guidelines for SMBG, and potentially inform health policy pertaining to strip reimbursements for T2DM patients that are not treated with insulin." (PMID 27542325, 2016).
diabetes (continued). "Compared with age- and BMI-matched IS participants, all IR (non-diabetic IR + type 2 diabetes mellitus) individuals had higher plasma levels of total cholesterol, triacylglycerols, FPG and insulin." (PMID 27342408, 2016). "STZ destroys the insulin-producing beta cells of the pancreas; therefore, mice receiving STZ develop type 1 diabetes mellitus owing to a lack of insulin secretion rather than through the de novo development of insulin resistance." (PMID 27296438, 2016). "In multivariate analysis, gain in VO2 peak was associated with final fructosamine level (p = 0.010) but not with age, gender, duration of diabetes, type of ACS, insulin treatment or basal fructosamine." (PMID 26152221, 2015). "The basal dose of insulin, proportion of total daily insulin, and circadian variation during continuous subcutaneous insulin infusion (CSII) therapy among children with type 1 diabetes mellitus (T1D) have not been fully elucidated." (PMID 25802842, 2015). "In the absence of diabetes, AGE-mediated decreases in insulin sensitivity and signaling have been postulated." (PMID 26223897, 2015). "Our study including 1,568 men without diabetes found impaired β-cell secretion in current smokers, which was signified by both low values of HOMA-β and fasting insulin." (PMID 26236748, 2015). "Medline and Embase databases were searched for studies by typing ‘diabetes and percutaneous coronary intervention/PCI’ or ‘insulin-treated and non-insulin treated diabetes mellitus and PCI’." (PMID 26446829, 2015). "Thus phosphorylation and inhibition of TCTP by insulin may serve as potential targets for therapeutic interventions to mitigate TCTP-related diseases and conditions that might include vascular hyperreactivity, sodium pump dysregulation, hypertension, and diabetes mellitus." (PMID 25854427, 2015). "Similar to continuous light exposure, effects of this light shift model on glucose metabolism were only observed in diabetes-prone HIP rats but not in wild type rats (increased glucose levels and decreased glucose- and arginine- stimulated insulin secretion)." (PMID 25852554, 2015). "Diabetes in dogs strongly resembles human type 1 diabetes mellitus (T1DM), with progressive onset of hyperglycemia, polydipsia, polyuria, ketonuria, diabetic ketoacidosis, and death without lifetime injected insulin therapy." (PMID 26057531, 2015). "Presurgery OGTT measurements of plasma insulin and ITT were performed on rats in the 12th week of life with and without diabetes." (PMID 26185767, 2015). "Data from large studies, such as the Diabetes Control and Complications Trial (DCCT) and United Kingdom Prospective Diabetes Study (UKPDS), suggest that intensive treatment itself (using insulin or not) does not impair HRQoL." (PMID 26110026, 2015). "In our cohort, all patients, irrespective of whether they had DM, prediabetes or normoglycemia by one or more criteria, had BG excursions above 140 mg/dl right after surgery, requiring an insulin infusion as per our institutional cutoff." (PMID 26322019, 2015). "In a recent study of patients with and without diabetes, intraoperative GLP-1 in addition to a standard insulin protocol achieved better glucose control in the GLP-1 group during the CABG period (p = 0.009)." (PMID 28702223, 2015). "It should be pointed out that, differently to many current therapies for diabetes, the mechanism of action of SGLT2 inhibitors is independent of insulin secretion or action and, therefore, it does not depend on beta-cell function." (PMID 25785281, 2015). "Type 2 diabetes mellitus (T2DM) is a progressive disease, which requires insulin treatment when other management is no longer effective." (PMID 25585592, 2015). "Echuim oil also has been shown to improve insulin sensitivity in non-human primates, and SDA has been proposed for the management and treatment of diabetes." (PMID 25515553, 2014).